LCK (LCK proto-oncogene, Src family tyrosine kinase)
Diseases named in the same sentence as LCK in open-access papers (continued):
Sharing a sentence is not in itself a finding about the gene and the disease.
osteosarcoma (1 paper, 2023). A usually aggressive malignant bone-forming mesenchymal neoplasm, predominantly affecting adolescents and young adults. "This leads to functional consequences as the inhibition of LCK, via shRNA or pharmacologic inhibitor, leads to inhibition of DNA damage repair as assessed using the established DR-GFP assay in U2OS osteosarcoma cells." (PMID 37370140, 2023).
ovarian dysfunction (1 paper, 2023). The inability of the ovaries to function. "Among the genes we identified through coexpression of three datasets, PNPLA3, MVD, MMP9, oncostatin M (OSM), LCK, triggering receptor expressed on myeloid cells 1 (TREM1), FADS2, proprotein convertase subtilisin/kexin type 9 (PCSK9), and C3 are involved in lipid metabolism and ovarian dysfunction." (PMID 37537636, 2023).
ovarian epithelial tumor (1 paper, 2022). A benign, borderline, or malignant tumor that originates from the surface epithelium of the ovary. "Patients with ovarian epithelial tumors exhibited significant amplification of LCK." (PMID 36430477, 2022).
pancolitis (1 paper, 2022). Ulcerative colitis that involves the entire colon. "In 66% of all investigated tissue slices of CerS4 LCK/Cre mice, the inflammation extended from the distal to the proximal part of the colon (pan), while in CerS4 KO mice, about 50% of all slices exhibited pancolitis." (PMID 35163788, 2022).
pancreatic endocrine tumors (1 paper, 2020). "LCK is overexpressed in pancreatic endocrine tumors, although significant associations between LCK and clinical outcomes have not been identified." (PMID 33233470, 2020).
Pruritus (1 paper, 2022). Pruritus is an itch or a sensation that makes a person want to scratch. "LCK, AMD1, and MAPKAPK2 might be possible oxymatrine targets in the treatment of pruritus." (PMID 36210824, 2022).
Richter syndrome (1 paper, 2017). Transformation of chronic lymphocytic leukemia into aggressive non-Hodgkin's lymphoma, usually diffuse large B-cell lymphoma (immunoblastic or centroblastic variant). "Furthermore, our analysis documents that NFAT2 and LCK expression are significantly downregulated in patients with Richter’s syndrome, a similar transformation which occurs in up to 10% of human CLL patients." (PMID 28970470, 2017). "To assess whether the NFAT2-LCK axis also possesses a function in human CLL, we determined NFAT2 and LCK expression levels in lymph node biopsies from patients with indolent CLL and Richter’s syndrome." (PMID 28970470, 2017). "Interestingly, NFAT2 as well as LCK were clearly overexpressed in patients with indolent CLL and the typical anergic phenotype, whereas a substantial downregulation of these two proteins could be detected in patients with Richter’s syndrome." (PMID 28970470, 2017).
serous ovarian cancer (1 paper, 2023). "We developed and validated a multimodal radiomic machine learning approach to noninvasively predict the expression of lymphocyte cell-specific protein-tyrosine kinase (LCK) expression and clinical prognosis of patients with high-grade serous ovarian cancer (HGSOC)." (PMID 37773310, 2023).
T-cell immunodeficiency (1 paper, 2024). A broad classification of disorders that affect the cell-mediated aspect of the immune response. "Indeed, two human LCK mutations have been found to be associated with T cell immunodeficiency." (PMID 37962568, 2024).
thymic lymphoma (1 paper, 2022). "In line with this, we further demonstrated that LCK‐mediated RIPK3 activation inhibits thymic lymphoma development through the attenuation of ERK activation." (PMID 36161785, 2022).
thyroid cancer (1 paper, 2021). "Another study by Silvia and co-workers demonstrated that LCK kinases are involved in regulating the progression of thyroid cancer." (PMID 33345267, 2021).
triple-negative breast carcinoma (1 paper, 2023). An invasive breast carcinoma which is negative for expression of estrogen receptor (ER), progesterone receptor (PR), and human epidermal growth factor receptor 2 (HER2). "LCK has been identified as a gene that plays the role of a master regulator in neutrophil enrichment and polarization towards either pro- or anti-inflammatory states in triple-negative breast cancer." (PMID 37686072, 2023).
tumor (113 papers, 2003 to 2026). "ITGA5 and SLC7A1 were found to be overexpressed in CC tumor tissues and were associated with a worse prognosis, except for LCK, GCH1 and TNFRSF9." (PMID 38903179, 2024). "Second, both genes associated with T-cell activation and response, like LCK, and genes involved in other aspects of tissue organization and tumor biology, like TP63, have roles in immunotherapy response." (PMID 38793063, 2024). "As shown, LCK most highly correlated with the infiltration of M1-like macrophages and CD8+ T cells, which indicated LCK played an important role in tumor-associated immune cell infiltration in most solid tumors." (PMID 36561315, 2022). "Pathway analysis showed that high expression of LCK was significantly associated with activation of multiple tumor pathways as well as immune-related pathways." (PMID 36341345, 2022). "In STS patients, the expression level of LCK significantly correlated with tumor-associated M1-like macrophage infiltration (p = 1.33 × 10−44; r = 0.73)." (PMID 36561315, 2022). "In addition, we also found that the CD3D, CD3E and LCK expression was significantly negatively related to tumor purity while positively associated with the infiltrating levels of immune cells, such as B cell, CD8 + T cell, and CD4 + T cell." (PMID 33748188, 2021). "Therefore, our study focused on the differential analysis of the immune-related components in the tumor microenvironment, and explored their associations with LCK expression, survival outcomes, tumor characteristics, and immune cell infiltration in patients with HGSOC." (PMID 37773310, 2023). "For instance, BBεζ CARs, which combine a 4-1BB co-stimulatory domain with CD3ε and ζ chains, exhibit superior anti-tumor activity in leukemia models compared to BBζ CARs by recruiting LCK through the RK motif." (PMID 41601693, 2026). "CD28 facilitates LCK-mediated phosphorylation of the CD3ζ chain, promoting immediate T-cell activation and rapid tumor-killing by CAR T-cells." (PMID 40298832, 2025). "For example, the loss of proto-oncogene LCK accelerates CLL development in mice, suggesting the tumor suppressor role for this gene." (PMID 39189258, 2024). "PNT can also reduce the efficiency of MHC I binding with peptides on the membrane of cancer cells, nitrating CCL2, STAT1, and Lymphocyte cell-specific protein-tyrosine kinase (LCK) to inhibit anti-tumor immunity." (PMID 38720342, 2024). "Studies have found that the cluster of differentiation 146 (CD146) combined with lymphocyte cell kinase (LCK) can promote the initiation of T cell receptor signaling and anti-tumor immune response in mice." (PMID 36878930, 2023). "For example, the LCK pathway is activated among basal cells, T cells and NK cells in recurrent tumours." (PMID 37488671, 2023). "Abnormally high expression of LCK in HGSOC patients is significantly correlated with the tumor immune microenvironment and can be used as an essential indicator for predicting the prognosis of HGSOC." (PMID 37773310, 2023). "LCK positive tumor cells were observed and LCK protein was distributed in the cytoplasm as well as the nucleus." (PMID 37370140, 2023). "This evidence suggests that LCK likely functions not only by the intrinsic properties of cancer cells but also by the components in the tumor microenvironment (TME)." (PMID 36430477, 2022). "Among post-radical CCA resection patients, high Lymphocyte-specific protein tyrosine kinase (LCK) and Circular Alpha-actinin-4 (circACTN4) expression are related to early tumor recurrence and worse prognosis, respectively." (PMID 36033517, 2022). "We further explored the promoter methylation level of LCK in LIHC based on tumor grade and stage, and found that higher grades of tumors were usually associated with lower levels of promoter methylation in LIHC." (PMID 36430477, 2022).
tumor (continued). "LCK is a key signalling molecule that functions in T cell maturation, mediates T cell metastasis and enhances the anti-tumour effects of T cells in response to stimulation by chemokines." (PMID 36291944, 2022). "The relationship between LCK expression and tumor stage in remission should be further investigated." (PMID 36430477, 2022). "Jonas and co-workers identified LCK as a driver for the invasion and migration of oral cancer by exploiting tumor heterogeneity." (PMID 36430477, 2022). "We then analyzed the correlation between LCK expression levels and four clinical parameters, including tumor status, metastasis, pathological stage, and the extent and size of the primary tumor." (PMID 36341345, 2022). "Because LCK is known to be deubiquitinated in vivo, it is possible that USPs act on LCK as part of their role in promoting tumor survival." (PMID 36490346, 2022). "In the present study, it was found that the expressions of CXCR4 and LCK in the tumor tissue of the Hespintor treatment group were significantly higher than those of the solvent control group, which appeared to be contrary to the general theory." (PMID 33391431, 2021). "Upregulation of MHC-II expression enhances antigen presentation and prevents tumor immune escape regarding adaptive immune responses, in which the Src-family tyrosine kinase LCK activates T cell receptors and enhances immune responses." (PMID 34708131, 2021). "For example, the levels of PTEN (a tumor suppressor gene), LCK and Syk (two immune-related genes) and has-miR-151-5p (related to tumor invasion and metastasis) was completely inconsistent." (PMID 32874774, 2020). "Taken together, these results demonstrate that PTPN2 deficiency promotes the LCK‐dependent activation of CAR T cells and overcomes the immunosuppressive tumour microenvironment to eradicate solid tumours in vivo." (PMID 31803974, 2020). "CAR T cells are autologous T cells engineered to express a transmembrane CAR specific for a defined tumour antigen that signals via canonical TCR signalling intermediates such as LCK." (PMID 31803974, 2020). "The present study reveals phosphorylation of FOXP3 by LCK, a Src family kinase that modulates tumor progression." (PMID 24155921, 2013). "We verified the involvement of T-cell receptor signaling pathways in HNSCC as well as associated oncogenes such as LCK and PLCB1, and tumor suppressors such as STAT5A, PTPN6, PARK2." (PMID 21884569, 2011). "Additionally, TGFB2 methylation correlates inversely with numerous T cell receptor (TCR) signaling components—HLA-D molecules, CD3D, CD28, and LCK—all of which are upregulated in the tumor when TGFB2 is weakly methylated." (PMID 40650134, 2025). "Moreover, the lymphocyte cell‐specific protein tyrosine kinase LCK phosphorylates the ZAP70 protein (ζ chain of TCR‐associated protein kinase 70), and we measured a fourfold increased LCK activity in tumour biopsies of LC patients." (PMID 39995112, 2025). "Finally, in Reverse Phase Protein Array (RPPA) of SKCM cohorts, the protein levels of LCK and CD20 were higher in low-risk group, suggesting a boost of the anti-tumor immune response." (PMID 38438381, 2024). "Specifically, in the tumor from patient #7, genes involved in T cell activation and signaling such as PTPRC (which encodes CD45), LCP2, FYB, CD3E, and LCK, and in genes involved in immune response and interferon signaling such as STAT1, OAS2, and HLA were downregulated." (PMID 37620318, 2023). "Interestingly, LCK showed a similar pattern of upregulation in DLBCL tumor samples as BTK and SYK, both of which drive the BCR signaling pathway and are therapeutic targets in B-cell malignancies." (PMID 36711753, 2023). "Moreover, small-molecule inhibitors targeting LCK in human tumor cells have exhibited remarkable therapeutic effects." (PMID 36430477, 2022).
tumor (continued). "Targeting the inhibition of the LCK-14-3-3ζ-TRPM8 axis to impair oncogene function of both TRPM8 and LCK may enhance tumor sensitivity to therapeutics, allowing for potential pharmacological targeting for anticancer therapy." (PMID 35665750, 2022). "Our results demonstrate that the expression of LCK is positively correlated with that of chemokines, that LCK is a key signalling molecule in T cell maturation, and that chemokines can further enhance T cell metastasis and anti-tumour activity by stimulating LCK expression." (PMID 36291944, 2022). "In addition, a seven-metagene cluster (STAT1, interferon, HCK, MHC-I, MHC-II, IgG, and LCK) has been reported in several studies to illustrate the inflammatory activities in the tumor microenvironment." (PMID 35222371, 2022). "Therefore, we assumed that LCK potentially induced M1-like macrophage infiltration in tumor tissue via specific downstream signaling pathways." (PMID 36561315, 2022). "Moreover, we analyzed the relationship between LCK and immune infiltration in different tumor types." (PMID 36430477, 2022). "Patient samples were used to detect LCK expression in tumor and normal tissues." (PMID 36430477, 2022). "Interestingly, we found that across most tumor types with statistical differences (p < 0.05), LCK promoter methylation was significantly lower than that in normal tissues, except for KIRP and PRAD." (PMID 36430477, 2022). "In addition, a growing number of studies have shown that LCK is also expressed in brain and tumor cells, where it is actively involved in the regulation of cellular functions such as proliferation and survival." (PMID 36341345, 2022). "Notably, the expression levels of CD3E, CCL5, CXCR6 and LCK in tumor samples and adjacent non-tumor samples were markedly different, and the results were consistent with the results of the analysis using TCGA." (PMID 34218795, 2021). "This study suggests that therapeutic strategies directed against LCK might not only show effects on tumor metastasis, but could also inhibit tumor growth." (PMID 34116687, 2021). "Importantly, LCK was consistently higher expressed across all tumor stages, grades and nodal status compared to normal tissue control." (PMID 34116687, 2021). "Targeted inhibition of LCK results in inhibition of tumor-sphere formation in cancer stem cells." (PMID 33233470, 2020). "The role that LCK plays in cancer progression may be complicated by opposing roles in tumor infiltrate and in tumor cells." (PMID 33233470, 2020). "LCK is a regulatory factor in hypoxia-induced tumor progression and angiogenesis." (PMID 32947901, 2020). "Additionally, LCK, a crucial component of T cell receptor signaling pathways, may influence T cell activation and anti-tumor immune response." (PMID 40708839, 2025). "Furthermore, elevated CDC6 expression may promote tumor cell proliferation by regulating the cell cycle (Borlado and Méndez, 2008), while high LCK expression may enhance T cell activity, thereby improving immunotherapy efficacy." (PMID 40708839, 2025). "Moreover, disruption of the interaction between co-receptors and LCK might modulate the balance between cytotoxic and helper T cell responses, which could be beneficial in the tumor treatment." (PMID 36564464, 2023). "Additionally, we performed correlation analysis to corroborate the relationship between tumor infiltrated immune cells and the expression of the seven key hub genes (CTLA4, PRF1, LCK, CD3E, CD247, ZAP70, and LCP2) in ARID1A-PIK3CA mutational co-occurrence tumors." (PMID 38017109, 2023). "Interestingly, the pan-cancer analysis also revealed a markedly favorable survival in tumors with high LCK expression, which indicated that LCK might participate in tumor growth inhibition." (PMID 36430477, 2022). "Therefore, whether LCK may promote the formation of TLSs and increase the anti-tumour function of TLSs through N1-TAN induction of CCL3, CXCL9 and CXCL10 aggregation remains to be further investigated." (PMID 36291944, 2022).
tumor (continued). "Additionally, functional annotation further suggested that CD3E, CD3D, and LCK were involved in positive regulation of T cell activation and leukocyte cell-cell adhesion that were known as the chief determinant for the efficacy of tumor immunotherapy." (PMID 33748188, 2021). "However, tumor cells also expressed LCK, albeit to a lesser extent." (PMID 34116687, 2021). "In addition to the important role of LCK in the function of T lymphocytes, there is increasing evidence that LCK is also widely expressed in brain and tumor cells, and it actively participates in signal transduction processes such as cell proliferation, survival, and memory." (PMID 32237064, 2020). "We could show that LCK expression significantly increased the tumor size in xenografted mice." (PMID 29062038, 2017). "We demonstrated a detrimental effect of G3P on CD8+T cells, as its interaction with LCK inhibits TCR signaling, rendering these cytotoxic cells ineffective in targeting tumor cells." (PMID 39848960, 2025). "In these studies, LCK KO allogeneic CAR T cells showed higher persistence and tumor control compared to TCR KO cells, indicating their possible roles for further investigation." (PMID 41354926, 2025). "LCK, a member of the SRC family kinases, can be targeted by inhibitors to disrupt cell signal transduction, thereby inhibiting tumor cell proliferation and survival." (PMID 40170854, 2025). "In this study, the inflammatory response genes (ITGA5, LCK, GCH1, TNFRSF9 and SLC7A1) play different role in immune tumor microenvironment." (PMID 38903179, 2024). "Activated LCK signaling can potentiate CD8+ T cell activation and anti-tumor responses thereby improving survival." (PMID 38561388, 2024). "VAV family proteins, CD3g, ZAP70 and LCK were down-regulated at four weeks in comparison to one week, suggesting a downregulation of T-cell response in PAK4KO tumour over time." (PMID 38797819, 2024). "High Asparagine levels enhances endogenous tyrosine lymphocyte-specific protein tyrosine kinase (LCK) signaling to potentiate CD8+ T-cell activation and anti-tumor responses." (PMID 38702616, 2024). "Malignant cell clusters shared cancer characteristics and widely significantly overexpressed HLA-A, HLA-B, MCL1, HDAC1, LCK, HSPB1, and IL6R, indicating a common tumor origin." (PMID 36131282, 2022). "In normal and tumor tissues, differential expression analysis based on TCGA cohort and GTEX cohort showed that LCK was highly expressed in tumor tissues (p-value< 0.05)." (PMID 36341345, 2022). "Lastly, in CR-TNBC patient P942, the baseline PDX tumor (BTY14) had high phosphorylation on the shared pTyr sites of SRC, FYN, LCK, YES1, and FGR as well as SFK substrates such as tensin, SHIP-1 (INPP5D), AFAP1L2, paxillin, and PTK2." (PMID 36077757, 2022). "These metagene clusters (HCK, Interferon, MHC-I, MHC-II, IgG, LCK, and STAT1) have previously been reported to represent various tumor inflammatory activities." (PMID 36439943, 2022). "The ionic interaction between LCK and CD3E controls the TCR phosphorylation, which is considered as the initial step in T-cell signaling to trigger adaptive immunity against tumor cells." (PMID 35004669, 2021). "We characterized the kinase-signaling network, where we identified LCK and EGFR as interconnected, down-regulated kinases and the tumor suppressors ATM and CDK2 as interconnected, up-regulated kinases." (PMID 34238254, 2021). "The expression of LCK and CD3E was found to be much lower in tumor samples than in normal samples, with a median expression value (transcript per million) of 6.685 vs 3.116 for LCK and 17.484 vs 5.58 for CD3E." (PMID 35004669, 2021). "TAP2 (P < 0.001; Cor = 0.60), PSME2 (P < 0.001; Cor = 0.52), HLA - E (P < 0.001; Cor = 0.69), and LCK (P < 0.001; Cor = 0.69) positively related to CD8+ T cell and negatively correlated with tumor purity." (PMID 33692827, 2021).